TNF (tumor necrosis factor)
Diseases named in the same sentence as TNF in open-access papers (continued):
Sharing a sentence is not in itself a finding about the gene and the disease.
rheumatoid arthritis (continued). "Previously, we showed that DcR3, which is overexpressed in rheumatoid arthritis fibroblast-like synoviocytes (RA-FLS) and further induced by TNFα, protects cells from Fas-induced apoptosis." (PMID 38401037, 2024). "Similarly, another study reported a dual approach of PEI-modified PLGA nanoparticles to deliver dexamethasone and anti-COX-2 siRNA to the human chondrocyte cell line C28/12, in which rheumatoid arthritis (RA) conditions were induced by TNF-α treatment." (PMID 38255196, 2024). "However, a study involving long-standing, incident, and anti-TNFα-treated cohorts of rheumatoid arthritis patients, linked with the Swedish Cancer Registry, concluded that the risk of lymphoma in anti-TNFα-treated patients was not higher compared to other cohorts." (PMID 38610706, 2024). "In conclusion, this TNFα antagonist would be helpful for the prevention and repair of inflammatory bone destruction and subsequent loss in the mouse model of CIA as well as human rheumatoid arthritis (RA) patients." (PMID 38839973, 2024). "and Jaspis. sp., and in an in vivo rat model of complete Freund’s adjuvant rheumatoid arthritis (RA), showed it acted as a SphK1 inhibitor in vitro and significantly improved RA symptoms measured by decreased pro-inflammatory cytokines TNF-α, IL-6, and IL-1β, swelling volume, and arthritis score." (PMID 39057418, 2024). "The three most frequently enriched pathways for DEGs in the KEGG database were the TNF signaling pathway, PPAR signaling pathway, and Rheumatoid arthritis." (PMID 38469144, 2024). "Moreover, lactate has been involved in the activation of the NF-κB pathway induced by TNF-α in rheumatoid arthritis fibroblast-like synoviocytes (RA-FLSs)." (PMID 38540033, 2024). "Another study showed that a bs-Ab targeting TNF-α and IL-6 (TNF-α × IL-6)successfully inhibited CXCR-13 activity in both in vitro and in vivo models of rheumatoid arthritis." (PMID 39609700, 2024). "Multiple inflammatory diseases are characterized by dysregulation of tumor necrosis factor alpha (TNFα), and the development of anti-TNFα inhibitors has been a milestone in the treatment of rheumatoid arthritis (RA), inflammatory bowel disease, ankylosing spondylitis, and psoriatic arthritis." (PMID 40084239, 2024). "The aim of this study was to compare the risk of major cardiovascular events (MACE) and venous thromboembolic events (VTE) between tumour necrosis factor (TNF) and Janus kinase (JAK) inhibitors in patients with rheumatoid arthritis (RA)." (PMID 38756933, 2024). "Among patients with autoimmune diseases, especially rheumatoid arthritis (RA), the prevalence of DILD is 0.3-11.0% in those treated with methotrexate and 0.5-3.0% in those treated with anti-TNF agents." (PMID 39356911, 2024). "For the KEGG analysis, genes displayed notable enrichment in cytokine-cytokine receptor interaction, chemokine signaling pathway, IL-17 signaling pathway, TNF signaling pathway, PI3K-Akt signaling pathway, and rheumatoid arthritis (RA)." (PMID 39170615, 2024). "In the United States, the FDA approved the use of TNF-α inhibitors for the treatment of IBD, ankylosing spondylitis, psoriatic arthritis, and rheumatoid arthritis, with a few of these drugs predicted to have heart complications as potential side effects." (PMID 38611112, 2024). "The pleiotropic cytokine TNF-α plays a significant role in the pathophysiology of AS, inflammatory bowel disease (IBD), rheumatoid arthritis (RA), and various other immune-mediated or inflammation-related conditions." (PMID 39493161, 2024). "Specifically, it decreases the production of several cytokines, including IL-17, IL-6, IL-10, and TNF-α, as well as IFN-γ in rheumatoid arthritis (RA) patients and induces Tregs in certain experimental models." (PMID 38791521, 2024).
rheumatoid arthritis (continued). "Increased TNF-α release is clearly correlated with dysregulated ADAM17 activity in autoimmune conditions, such as rheumatoid arthritis (RA), SS, systemic lupus erythematosus (SLE), psoriasis, and Crohn’s disease (CD)." (PMID 39768182, 2024). "All patients were treated with anti-TNFα at the time of TB diagnosis: 42% for IBD, 20% for rheumatoid arthritis, 17% for spondyloarthropathy, 12% for psoriasis." (PMID 38957691, 2024). "Blocking TNF signaling through its receptors TNFR1 and TNFR2 has been widely targeted in clinical trials of autoimmune and inflammatory diseases, such as rheumatoid arthritis, Crohn’s disease, ankylosing spondylitis, psoriasis, and psoriatic arthritis." (PMID 38962007, 2024). "After eight weeks of quercetin treatment (500 mg/day) in women with rheumatoid arthritis, early morning stiffness (EMS), morning, and after-activity pain were reduced, and TNF-α levels were significantly decreased." (PMID 37432408, 2023). "TNF-α is an important inflammatory cytokine whose levels are increased in some autoimmune diseases, such as SLE, rheumatoid arthritis, and inflammatory bowel disease." (PMID 37355563, 2023). "Controlling inflammation with tumor necrosis factor (TNF) inhibitors in rheumatoid arthritis (RA) patients is hypothesized to reduce their cardiovascular risk." (PMID 36645550, 2023). "Etanercept is a TNF-alpha inhibitor that is FDA-approved for the treatment of psoriasis, rheumatoid arthritis, and ankylosing spondylitis." (PMID 37065345, 2023). "KEGG pathway analysis revealed that the pathways enriched by NETs-DEGs include ‘TNF signaling pathway,’ ‘NOD-like receptor signaling pathway,’ ‘IL-17 signaling pathway,’ ‘Rheumatoid arthritis,’ and ‘NF-kappa B signaling pathway’." (PMID 37932341, 2023). "There are cases of induction or exacerbation of psoriasis in patients with AS, rheumatoid arthritis, Crohn’s disease, and SAPHO syndrome, after receiving therapy with TNF-α inhibitors." (PMID 36983699, 2023). "In the past 20 years, the availability of tumor necrosis factor inhibitors (TNFis) and other biologic disease-modifying antirheumatic drugs (bDMARDs) has transformed treatment for patients with rheumatoid arthritis (RA)." (PMID 37382956, 2023). "Noteworthy examples include tumor necrosis factor-alpha (TNF-α), interleukin-1 beta (IL-1β), and IL-6, which are often elevated in disorders like rheumatoid arthritis (RA), intensifying inflammation and contributing to tissue damage." (PMID 37965323, 2023). "When the human cyclooxygenase-2 gene is silenced on cultured synovial cells of rheumatoid arthritis patients, there is a reduction of prostaglandin E2 (PGE2), vascular endothelial growth factor (VEGF), IL-1β, and TNF-α." (PMID 37446881, 2023). "Kaempferol, a flavonoid that is abundant in the KR inhibits the MAPK pathway prevented rheumatoid arthritis fibroblast-like synoviocytes (RA-FLSs) from migrating, invading, and expressing matrix metalloproteinases (MMPs), which markedly reduced the production of tumour necrosis factor (TNF-)." (PMID 36923360, 2023). "The current success of drugs blocking TNF-α as well as IL-17A receptors in the treatment of rheumatoid joints confirms that TNF-α and IL-17A mediated transmissions play a key role in rheumatoid arthritis." (PMID 37298893, 2023). "It has been shown that TNFα induces ER stress/UPR activation in murine fibrosarcoma L929 cells, human osteoblast-like SaOs-2 cells, synovial fibroblasts from patients with rheumatoid arthritis, and human airway smooth muscle cells." (PMID 36760534, 2023). "Cellular inflammatory mediators, including cytokines such as interleukin (IL)-17, tumor necrosis factor-alpha (TNF-α), IL-6, and IL-8, can contribute to the development of rheumatoid arthritis." (PMID 37808603, 2023).
rheumatoid arthritis (continued). "Through regulation of various proinflammatory mediators, OSM in rheumatoid arthritis synovial fibroblasts (RAFLS), increases the detrimental effects of tumor necrosis factor alpha (TNFα) via activation of STAT3 signaling." (PMID 37841259, 2023). "Associations studies in a rheumatoid arthritis population have not demonstrated a relationship between sleep quality and methotrexate;73 however, in other prospective studies, introduction of methotrexate did not lead to any improvement in sleep quality—unlike introduction of TNF‐a inhibitors." (PMID 36968569, 2023). "Indeed, increased levels of TNF-α have been reported in cases of Alzheimer’s disease (AD), multiple sclerosis (MS) or rheumatoid arthritis (RA), among others." (PMID 37391534, 2023). "For example, in the context of rheumatoid arthritis, HIF-1α was shown to directly interfere with the production of TNF-α, IL-1β, IL-6 and IL-8." (PMID 38273861, 2023). "Recently, VHH Ozoralizumab (Nanozora), a novel tumor necrosis factor (TNF) inhibitor, was approved in Japan for the treatment of rheumatoid arthritis." (PMID 37834033, 2023). "In addition, VHHs targeting TNF may be suitable for the treatment of rheumatoid arthritis." (PMID 37686035, 2023). "A case study of a large rheumatoid arthritis patient population analyzed the frequency of serious adverse events in patients using TCZ (65,000 patient-years) in comparison to anti-TNFα (50,000 patient-years) therapies." (PMID 38106420, 2023). "Although the idea of blocking TNF-α seemed promising, this approach was seen to have little effect on IFP patients and was detrimental to individuals with rheumatoid arthritis who have PF." (PMID 37446227, 2023). "CQ and HCQ are commonly used in the management of several conditions which are related to elevated levels of tumor necrosis factor α (TNF-α), including malaria, discoid lupus arthritis, or rheumatoid arthritis." (PMID 37366873, 2023). "TNF-α mediates the joint inflammation in rheumatoid arthritis (RA)." (PMID 36875034, 2023). "Tumor necrosis factor-alpha (TNF-alpha) antagonist use is prevalent for the treatment of autoimmune diseases, including psoriasis, ankylosing spondylitis, and rheumatoid arthritis." (PMID 36874325, 2023). "In an animal model for rheumatoid arthritis (RA), treatment with FTI decreased synovial TNF and IL-1 mRNA expression dampening inflammation." (PMID 38993912, 2023). "Notably, high CTRP1 and CTRP6 serum levels are also associated with increased TNF-α, IL-1β, and IL-6 blood concentrations, and CTRP1 and CTRP6 serum levels are increased in patients suffering from chronic inflammatory diseases, such as rheumatoid arthritis and Kawasaki disease." (PMID 37047812, 2023). "Anti-tumor necrosis factor (TNF) therapies are the cornerstone of the treatment for IBD and other chronic inflammatory conditions, including rheumatoid arthritis and psoriasis." (PMID 38004593, 2023). "These pathways were primarily associated with the TGF-beta signaling pathway, NF-kappa B signaling pathway, JAK-STAT signaling pathway, TNF signaling pathway, PI3K-Akt signaling pathway, Rheumatoid arthritis, and Inflammatory bowel disease." (PMID 36624435, 2023). "Infliximab and adalimumab are specific for tumor necrosis factor (TNF) and are used for treating Crohn’s disease, rheumatoid arthritis, and plaque psoriasis." (PMID 37764213, 2023). "Currently, anti-TNF therapies are widely used as FDA-approved treatments for several diseases such as Crohn’s disease (CD), ulcerative colitis (UC), rheumatoid arthritis (RA), ankylosing spondylitis (AS), psoriatic arthritis, and plaque psoriasis." (PMID 37138340, 2023). "• TACE is an enzyme that converts TNF-α and releases TNF-α related to the membrane.• TACE inhibitors are promising and used in the clinic in rheumatoid arthritis, sepsis, other inflammatory disorders, and many aspects of cancer therapy." (PMID 36969193, 2023).
rheumatoid arthritis (continued). "Indeed, TNF-α antagonists have elicited great success in rheumatoid arthritis (RA), and various other immunotherapies have shown notable efficacy." (PMID 35076022, 2022). "Other studies show that rheumatoid arthritis synovial fibroblast (RASF), when exposed to TNF-α, increased the expression of miRNA146a." (PMID 35159262, 2022). "Among these potential therapeutic targets, the establishment of anti-IL-6 and TNF-α antibodies, as well as Janus kinase (JAK) inhibitor therapies for rheumatoid arthritis, have been the most successful." (PMID 35563063, 2022). "The reduction in pro‐inflammatory cytokine production has been observed in rheumatoid arthritis patients, in whom ω‐3 PUFA dietary supplementation decreased serum TNF concentration, IL‐1 production by monocytes, and plasma IL‐1β concentrations." (PMID 35600637, 2022). "Tumor necrosis factor alpha (TNFα) is a pleiotropic cytokine that has beneficial functions in immune regulation and host defense, but is also involved in a variety of inflammatory diseases, including rheumatoid arthritis (RA)." (PMID 35273620, 2022). "In mouse models of rheumatoid arthritis, ATX expression in synovial fibroblasts was stimulated by TNF, which is one of the crucial mediators for granuloma formation in sarcoidosis." (PMID 35288647, 2022). "Although the inhibitors of the interleukin-6 receptor (IL-6R) and tumor necrosis factor-α (TNF-α) have achieved a certain success in the clinical treatment of rheumatoid arthritis (RA), great effort should be made to overcome side effects and to improve patient compliance." (PMID 35890412, 2022). "The KEGG enrichment analysis indicated that the core IRGs enriched in TNF signaling pathway, IL-17 signaling pathway, Toll-like receptor signaling pathway, AGE-RAGE signaling pathway in diabetic complications, and Rheumatoid arthritis." (PMID 36389252, 2022). "The binding of TNF-α to TNF receptor (TNFR) activates the NF-κB pathway and induces chronic inflammatory diseases such as rheumatoid arthritis, inflammatory bowel disease, multiple sclerosis, and atherosclerosis." (PMID 35783508, 2022). "The elevated level of miR-155 correlates with the upregulation of TNF-α and the downregulation of SOCS1 in rheumatoid arthritis." (PMID 35563301, 2022). "Lymphatic dysfunction exists in tumor necrosis factor transgenic (TNF-Tg) mice and rheumatoid arthritis (RA) patients." (PMID 35255954, 2022). "In this prospective observational study, data were collected from 34 rheumatology clinics in Italy in patients with rheumatoid arthritis (RA), psoriatic arthritis (PsA) and axial spondyloarthritis (axSpA) who started golimumab (GLM) as a second anti-TNFα drug." (PMID 35887946, 2022). "Humanized anti-TNF-α monoclonal antibodies (anti-TNF-α mAB) such as infliximab are used in the treatment of rheumatic and autoimmune diseases, including rheumatoid arthritis or psoriasis as well as GI diseases such as CD and UC." (PMID 35328624, 2022). "In addition, TNF inhibitors have been introduced into the clinical treatment of rheumatoid arthritis (RA) for approximately 20 years." (PMID 36532774, 2022). "Anti-tumor necrosis factor alpha (TNF-α) agents are used in a variety of inflammatory diseases, including inflammatory bowel diseases (IBD), rheumatic diseases (rheumatoid arthritis (RA) and axial spondyloarthritis), and psoriasis." (PMID 35625771, 2022). "A variety of pro-inflammatory cytokines (e.g., interleukin-1 beta (IL-1b), tumor necrosis factor-alpha (TNF-a), and IL-6) are known to play prominent roles in the progression of inflammatory diseases such as rheumatoid arthritis, pneumonia, and gout." (PMID 35216342, 2022). "TNF-α helps produce SR-A, participating in the production of CCL-2, which is a key player in rheumatoid arthritis and can stimulate chemotaxis in mononuclear cells." (PMID 36297105, 2022).
rheumatoid arthritis (continued). "Knowing that miRNA172 regulates the TNF-α signaling pathway via the FAN protein, we chose an animal model of rheumatoid arthritis, as the disease is strongly dependent on TNF-α signaling." (PMID 35401203, 2022). "TNF-α inhibitors are widely used in rheumatoid arthritis (RA) with varying success." (PMID 35219333, 2022). "Autophagy was activated in the osteoclasts of human rheumatoid arthritis by upregulating ATG7, and ATG7 overexpression decreased osteoclastogenesis and TNFα-induced bone erosion." (PMID 36358952, 2022). "In mouse models with rheumatoid arthritis, ATX proteins are expressed on synovial fibroblasts and its expression is markedly stimulated by TNF, which is one of the crucial mediators for granuloma formation." (PMID 35288647, 2022). "The KEGG analysis demonstrated that NOD-like receptor signaling pathway, IL-17 signaling pathway, cell cycle, rheumatoid arthritis, ECM–receptor interaction, and TNF signaling pathway were enriched." (PMID 35874675, 2022). "Biological inhibitors such as tumor necrosis factor (TNF) and interleukin- (IL-) 6 inhibitors can relieve the inflammatory symptoms in rheumatoid arthritis, but their efficacy is limited in OA." (PMID 35087596, 2022). "Drugs capable of neutralizing TNF-α, such as etanercept, a fusion protein of soluble TNF-α receptor 2 and IgG1 FC-terminal, have been used clinically to treat diseases such as rheumatoid arthritis and psoriasis." (PMID 35894345, 2022). "We demonstrated that in RASFs, which contribute to joint breakdown in rheumatoid arthritis, PINK1 knockdown decreased cell invasion and migration, including under TNF-α stimulation." (PMID 35628458, 2022). "IFN pathway is closely related to the pathogenesis of rheumatoid arthritis and induces IFN response genes in synovial fibroblasts after TNF stimulation." (PMID 36468006, 2022). "It has also been reported that TNF-α induces expression of VEGF, and that VEGF induces TNF-α expression, in the synovial fluid of rheumatoid arthritis patients." (PMID 35028065, 2022). "At that time, almost all the scientific papers on rheumatoid arthritis started with the sentence “TNF is a key cytokine in RA development”, suggesting that we had finally found the ‘holy grail’ and that we would be able to successfully treat all inflammatory conditions." (PMID 36015084, 2022). "Infliximab (INF) is one of the five tumor necrosis factor-α (TNF) inhibitors that is routinely used for indications of chronic inflammatory diseases such as rheumatoid arthritis (RA), inflammatory bowel disease (IBD), ankylosing spondylitis (AS), and psoriatic arthritis (PsA)." (PMID 36316762, 2022). "TNF signaling is a significant part of the inflammatory process, and TNF-α plays a determinate role in the pathogenesis of several inflammatory diseases such as rheumatoid arthritis (RA), psoriatic arthritis, and ankylopoetica spondylarthritis." (PMID 36248423, 2022). "On the other hand, it has been reported that TNF-α and IL-6 upregulate the expression of the chemokine receptors CCR5 and CXCR3 on Vδ2 T cells in patients suffering from rheumatoid arthritis." (PMID 34900753, 2021). "For rheumatoid arthritis (RA), three JAK inhibitors and a range of bDMARDs are approved, including those targeting TNFα, IL-6, IL-1β, B cells (CD20), and T cells (CD80/CD86)." (PMID 34290741, 2021). "TNF-α is a powerful proinflammatory cytokine, which plays an important role in the pathogenesis of graft-versus-host disease and chronic inflammatory diseases (such as rheumatoid arthritis (RA) and inflammatory bowel disease)." (PMID 33553436, 2021). "In rheumatoid arthritis, CCR1 regulates the expression of TNFα and IL-10, and is therefore an efficient therapeutic target." (PMID 33509198, 2021). "TNF inhibitors, including etanercept, infliximab and adalimumab, are FDA-approved for the treatment of multiple inflammatory conditions like rheumatoid arthritis." (PMID 33948920, 2021).